IL15 (interleukin 15)
Diseases named in the same sentence as IL15 in open-access papers (continued):
Sharing a sentence is not in itself a finding about the gene and the disease.
tumor (continued). "Importantly, the application of the bicistronic TH/IL-15-based DNA vaccine significantly reduced tumor volume (Ub_hTH+mIL-15 vs. mIL-15, day 21, P<0.05)." (PMID 30452438, 2018). "We could demonstrate that the cultured UCB γδ T cells were based on gene expression and efficient cytokine producers, especially with regard to IL-1β, IL-2, IL-8, and IL-15, and had a capacity for killing tumor cells comparable to cultured PB γδ T cells." (PMID 29707004, 2018). "Taking into account that Avelumab treatment in combination with IL-2 or IL-15 may result in tumor cells being exposed to higher levels of IFN-γ derived from NK cells or CD8 T cells; we further studied in vitro the effect of combining both treatments." (PMID 30294328, 2018). "Thus, IL-15 has become a promising candidate for tumor immunotherapy; IL-15 administration is used to bolster immune responses and augment the tumor immune surveillance." (PMID 29255466, 2017). "In BT474 HTM, the tumor volume in tumor-bearing animals shrank from 3416 mm3 (+/- 1401, n=12) in control mice to 2800 mm3 (+/- 932; n=5) in trastuzumab-treated animals down to 192 mm3 (+/- 186; n=4) in IL-15/trastuzumab-treated mice." (PMID 27835865, 2017). "Finally, cytokines associated with T helper cell (Th) polarization, IL12p40 and IL15 were also found at lower concentrations in the spleen of both flank and orthotopic tumor-bearing groups when compared to sham." (PMID 27901481, 2017). "Finally, we addressed the in vivo anti-tumor efficacy of IL-15 + 21boost expanded NK cells if combined with ionizing radiation in a RMS xenograft model." (PMID 28659917, 2017). "In addition to the previously demonstrated superior T cell- and NK cell stimulatory properties and direct tumor cell killing capacity of IL-15 DCs, these findings further underscore their strong immunotherapeutic potential as next-generation DC-based vaccines." (PMID 28099143, 2017). "Despite preserving a higher proportion of early/central memory subsets that mediate improved tumor immunity in mice, transfer of Vγ2Vδ2 T cells expanded with IL-15 inhibited PC-3 tumor growth in NSG mice identically to equal numbers of Vγ2Vδ2 T cells expanded with IL-2." (PMID 28239463, 2017). "Additionally, the presence of IL-15 in the tumor microenvironment, decreases proliferation, and blood vessel formation." (PMID 28379958, 2017). "Rodent studies showed an anti-apoptotic role for IL-15 with anti-tumor activity." (PMID 28667255, 2017). "Moreover, IL-15 treatment significantly stimulated a human immune cell infiltration into the tumor cell loaded peritoneum of SK-BR-3 HTM." (PMID 27835865, 2017). "We observed the enhanced tumor growth in immunodeficient mice with human IL-15 treatment." (PMID 29255466, 2017). "In addition, the tumor burden in the lung of IL-15/trastuzumab-treated mice tended to be lower compared to control or trastuzumab-treated HTM." (PMID 27835865, 2017). "After observing decreased cancer cell proliferation and angiogenesis in mice treated with IL-15, we hypothesized that increased tumor growth could be attributed to other factors." (PMID 28379958, 2017). "Current research efforts include the development of cytokine variants with extended in vivo half-life and targeted action on precise lymphocyte subsets and tumor sites (i.e., engineered IL-2 “superkine,” IL-15Rα Sushi-Fc fusion protein; IL-15 tri and tetraspecific killer engagers)." (PMID 29181007, 2017). "Indeed, a membrane-tethered form of IL-15 on tumor-specific T cells demonstrated improved T cell survival and enhanced anti-tumor effectsin vivo due to the preferential growth of T memory stem cells." (PMID 29123649, 2017). "Bortezomib administration increased IFNγ and granzyme-B expression on Vβ8.1/2+CD8+T cells in tumor-bearing mice even in the presence of IL-12 and IL-15 neutralization antibody treatments, and restored them to the levels comparable to tumor-bearing mice treated with bortezomib only." (PMID 28052005, 2017).
tumor (continued). "We first tested the IL-15 dosage in vivo in tumor-bearing mice." (PMID 29255466, 2017). "In addition, IL-15 fused with the extracellular domain of NKG2D was shown to exhibit enhanced NK cell tumor infiltration and increased suppression of xenografted tumors growth in nude mice infused with human PBMC." (PMID 28702032, 2017). "It is known that IL-15 enhances NK cell activity, which suggests NK cells may play an important role in the observed tumor suppression." (PMID 29296227, 2017). "It was observed in nude mice inoculated with tumor cells that transfecting the cells with a gene encoding prototypical IL-15 did not yield a promising anti-tumor effect." (PMID 29296227, 2017). "Here, we demonstrated that the in vivo injection of recombinant human IL-15 (200 μg/kg) or murine IL-15 (3 μg/kg) to tumor-bearing NOD-SCID-IL2Rg−/− (NSI) mice resulted in increased tumor progression and CD45+ CD11b+ Gr-1+ CD215+ cell expansion in the tumors and spleen." (PMID 29255466, 2017). "Advanced dose-finding studies using HTM might help to identify an IL-15 concentration that efficiently triggers the anti-tumor defense accompanied by tolerable and manageable side effects." (PMID 27835865, 2017). "Several results proved the potential of IL-15 therapy in mediating tumor regression." (PMID 28927416, 2017). "Since mRNA electroporation is broadly accepted to introduce tumor antigens into DC, in situ cotransfection with immune-stimulatory molecules like IL-15 and IL-15Rα mRNA can be easily performed in one electroporation step, avoiding the need of time- and cost-consuming manipulations." (PMID 28785596, 2017). "IL-15 is known to activate NK cell function and suppress tumor growth." (PMID 28955340, 2017). "In this model, we could detect a significant anti-tumor activity of DLI with a combination of IL-15 SA." (PMID 28574833, 2017). "In our study it remains unclear, and therefore requires further investigation, whether the expression of IL15 and/or IL15Rα at the tumor site has any relevant/conditional effect in tumor growth inhibition." (PMID 26822794, 2016). "Notably, addition of IL-15 in the expansion cultures evoked a superior cytotoxic capacity of expanded γδ T cells at the 10:1 ratio for both tumor cell lines." (PMID 27686372, 2016). "Despite its promising anti-tumor immune capacity, IL-15 has been shown to exhibit a short half-life and high doses were required to achieve biological responses in vivo, hence resulting in clinical toxicities and limited anti-tumor responses in patients." (PMID 26910920, 2016). "Thus, NK cells cultured with IL-15/IL-18 and exposed simultaneously to both drugs were analyzed for their anti-tumor activity and proliferative capability." (PMID 27563819, 2016). "One potential advantage of delivering IL-15 directly to the tumor with TetraKE is that systemic exposure might be avoided reducing toxicity." (PMID 27650544, 2016). "This study also suggests that pretreatment of tumor-reactive T cells with rapamycin in combination with IL-15 administration may be a novel strategy to improve the efficacy of adoptive T cell therapy." (PMID 26824989, 2016). "Furthermore, the expression of IL15 in the tumor microenvironment by cancer cells has been described to potentiate antigen-independent T cell cytotoxicity and tumor eradication." (PMID 26822794, 2016). "For these reasons, IL-15 has long been speculated to have high therapeutic potential for long-term anti-tumor immunity." (PMID 26910920, 2016). "Given the importance of the adoptive transfer of NK cells in tumour immunotherapy, the optimal mTORC1 activation triggered by IL-15 may provide new strategies for the ex vivo expansion of NK cells." (PMID 27601261, 2016). "Thus, it would appear that the increased NK cell activation and IFN-γ+ cytotoxic T cells were induced by the secretion of IL15 in F-PLP/pIL15-treated tumor cells, thus generating an antitumor effect." (PMID 27438147, 2016).
tumor (continued). "This increased localized expression of IL-15 in the tumor microenvironment (ascites) could enhance antitumoral T-cell responses, while the increased serum levels may aid in the prevention of metastasis, thus jointly inhibiting tumor growth." (PMID 27438147, 2016). "Thus, preconditioning with IL-15 promoted a higher CART cell persistence in vivo along with improved antitumor immunity in tumor-bearing hosts." (PMID 27409425, 2016). "As for IL-2, systemic IL-15-mediated toxicity might be circumvented by tailoring tumor-specific T cells to express IL-15." (PMID 27656185, 2016). "Therefore, IL-21 exposed CART cells showed the greatest persistence in animal models and the administration of this cytokine in vivo supported greater tumor eradication than other cytokines, excluding IL-15." (PMID 27409425, 2016). "On the other hand, γδ T cells of remission patient Dr, of which both protocols had yielded sufficient γδ T cells for functional testing, exhibited an almost doubling in the number of IFN-γ positive cells when expanded in the presence of IL-15 and challenged with tumor cells." (PMID 27686372, 2016). "Importantly, the NKG2D–NKG2DL system and IL‐15 are important for tumour surveillance, which is necessary for the elimination of neoplastic cells." (PMID 27538697, 2016). "Since IL-15 activates anti-tumor effectors such as NK cells, γδ T lymphocytes, and memory phenotype CD8+ T cells and exerts more long-lasting antitumor effects, it might be especially suitable for immunotherapy of NMIBC." (PMID 27273619, 2016). "Thus, IL-15 regulates anti-tumor cytotoxicity and modulates the inflammatory tumor microenvironment." (PMID 27148488, 2016). "IL-15 has been shown to revive CD8+ T cells from an anergic state in tumor hosts." (PMID 26625316, 2016). "Among the signal transduction pathways triggered by the engagement of IL-15 receptor with its ligand, the PI3K–AKT–mTOR pathway seems to be critical for the IL-15-mediated activation of NK cells, therefore being responsible for efficient anti-viral and anti-tumor responses." (PMID 26257729, 2015). "In fact, tumor formation closely followed what was observed in IL-15 KO/MT mice." (PMID 25879689, 2015). "IL-15 is capable of stimulating the production of anti-tumor memory CD8 T cells." (PMID 25879689, 2015). "IL-15 KO/MT, MT and IL-15 TG/MT were followed for tumor formation and endpoint." (PMID 25879689, 2015). "The extensive histological differences between IL-15 TG/MT and IL-15 KO/MT mice indicated that IL-15 may play a role in tumor formation and progression to endpoint." (PMID 25879689, 2015). "It is possible that tumour cells secreting pro-inflammatory cytokines, such as IL-15 which also enhances nitric oxide production, may influence phosphorylation of iNOS by Src in lung tissue epithelium 114,115." (PMID 25598217, 2015). "The superior tumor-cell killing effect of IL-15/IL-15Rα EP DC/NK-cell cocultures leveled out to the cytotoxic level of IL-15 EP DC/NK-cell cocultures using transwells, indicating that a contact-dependent IL-15 transpresentation mechanism is involved in the superior killing effect (p < 0.001)." (PMID 26675759, 2015). "However, in situ production of IL-2 and IL-15 is necessary to continually reactivate infiltrating NK cells to prevent NK cell exhaustion and inhibition by the tumour milieu suppressor cells and humoral factors, such as TGF-β." (PMID 26040463, 2015). "It has been proposed recombinant IL-15 may kill tumour cells by stopping the blood flow to the tumour and by stimulating white blood cells to kill kidney cancer cells (according to clinical trial NCT01727076)." (PMID 25598217, 2015). "In the intestine, subsets of ILC1 are also cytokine producers (IFN-γ and TNF-α) after in vitro stimulation with IL-12 + IL-15 or IL-12+ IL-18 or after mucosal infection.They can also also degranulate after in vitro stimulation in the presence of tumor cell line." (PMID 26630176, 2015).
tumor (continued). "We compared survival curves and tumor formation in IL-15 KO/MT, MT and IL-15 TG/MT groups." (PMID 25879689, 2015). "However, in situ production of interleukin-2 (IL-2) and IL-15 is necessary to continually reactivate these infiltrating NK cells to prevent NK cell exhaustion and inhibition by the tumour milieu suppressor cellular and humoral factors." (PMID 26040463, 2015). "Despite the fact that CFSE labelled CD8 T cells were present in the spleen and tumor at endpoint (data not shown), there was no impact on survival from transfer of either IL-15 TG/MT, MT or IL-15 TG splenic CD8 T cells or IL-15 TG/MT tumor CD8 T cells after a subcutaneous primary MT tumor injection." (PMID 25879689, 2015). "Therefore, NK1.1+ cells play a major role in the tumor destruction and extension of survival in IL-15 TG/MT mice, whereas CD8 T cells, although activated phenotypically, play less of a role." (PMID 25879689, 2015). "For example, several studies found that IL-15 TG mice were resistant to engrafted tumor formation." (PMID 25879689, 2015). "An attractive hypothesis would be that factors in the brain of EE mice inhibit the acquisition of a pro-tumour phenotype by CD11b+ M/Mφ, thus enhancing their capacity to produce IL-15 in response to tumour cells." (PMID 25818172, 2015). "In addition, IL-16 can activate the secretion of tumor-associated inflammatory cytokines, such as TNF-α, IL-1β, IL-6, and IL-15, all of which are major factors involved in tumorigenesis." (PMID 25954818, 2015). "We next tested whether additional stimulation of IL-15 DC-exposed NK cells with K562 tumor cells could trigger IFN-γ secretion." (PMID 25951230, 2015). "Thus, IL15 combined with tumor-specific mAb appears to merit clinical testing as a potential immunotherapy, which is currently underway (NCT02384954)." (PMID 26284063, 2015). "IL-15-deficient HER2/neu transgenic mice showed an earlier mammary carcinogenesis, with median latency time of tumor onset 4 weeks before that of IL-15-proficient NeuT mice, suggesting a role for IL-15 in tumor immunosurveillance." (PMID 25997501, 2015). "Of these cytokines, IL-15 is widely tested in CIK cells preparation against several tumor cells." (PMID 25108500, 2014). "Whether or not HPV vaccines can unlock the intrinsic cytotoxic effector function of IL-15 DC against HPV-positive tumour cells remains to be investigated." (PMID 24979331, 2014). "As the HPV vaccine is capable of unlocking the cytotoxic function of IL-15 DC against HPV+ tumour cells and as cytotoxicity is further increased after NK/DC coculture, the HPV vaccine might have therapeutic effects." (PMID 24979331, 2014). "IL-15 is already recognized as a promising candidate for tumor immunotherapy." (PMID 24416335, 2014). "Furthermore, the addition of IL-7 or IL-15 was shown to abrogate the suppressive activity of Tregs in vitro and the administration of anti-IL-2 plus exogenous IL-15 to tumor-bearing mice enhanced the adoptive immunotherapy of tumors." (PMID 24748966, 2014). "Although IL-21R−/− mice have normal NK cell numbers, treatment of murine NK cells in vitro with IL-21 reduces NK cell proliferation and survival in the presence of IL-2 or IL-15 but induces terminal differentiation and enhances NK cell cytotoxicity against tumor lines." (PMID 25054077, 2014). "Our results suggest that virally delivered IL15Rα-IL15 drives the recruitment of NK cells and T cells to the site of the tumor and that both the innate and adaptive components of the host immune system play a role in the anti-tumor effect." (PMID 25329832, 2014). "Similarly, mice bearing P1A+ tumors treated with TCR-transgenic T cells and low-dose IL-15 had longer persistence of tumor-specific CD8+ T cells compared to controls." (PMID 23418547, 2013). "Additionally, gene therapy approaches delivering IL-15 DNA to tumors using plasmid vectors or engineered viruses have successfully reduced tumor burden." (PMID 24312353, 2013).
tumor (continued). "However, in our large established tumor model where animals die at an early time point, we were unable to evaluate the long-term antitumor memory effects of IL-15 vs. IL-2." (PMID 24391824, 2013). "However, IL-15 produced in the tumor microenvironment can stimulate anti-tumor immune responses that improve survival." (PMID 24312353, 2013). "Tumour- associated glycoprotein-72 (TAG-72) enhances the already established tolerogenic features of decidual dendritic cells with the inability to progress towards Th1 immune orientation due to lowered interferon (IFN)-γ and interleukin (IL)-15 expression." (PMID 23864879, 2013). "However, HLA class I blocking on HTB-186 and overnight incubation with IL-15 stimulated NK cells efficiently killed tumor cells in vitro." (PMID 23626949, 2013). "Administration of lowdose IL-15 has been shown to promote the persistence of adoptively transferred tumor-specific T cells in murine tumor models; however, the systemic toxicity and the expansion of unwanted cells, including regulatory T cells, limit the clinical value of this strategy." (PMID 22496835, 2012). "IL-15 has even been shown to be more effective than IL-2 for tumor growth inhibition." (PMID 22509395, 2012). "Although IL-15 is being currently used in clinical trials, the function of the cytokine on kidney's components has not been extensively studied; we thus investigated the role of IL-15 on normal and tumor renal epithelial cells." (PMID 22363690, 2012). "Therefore, both CD56+ and CD56− IL-15 DC fractions were co-cultured with the K562 tumor cell line and examined for lytic activity using a PI/Annexin-V-based flow cytometric lysis assay." (PMID 23284789, 2012). "Thus, TGF-β treatment inhibited the IL-15 induced expression of key activating receptors and cytotoxic components involved in the detection and destruction of tumour cells." (PMID 21909397, 2011). "Thus, even in the setting of advanced ovarian tumors, CD8+ T cells mounted potent anti-tumor responses provided that IL-2/IL-15 signaling pathways were intact." (PMID 21203522, 2010). "Furthermore, there was an increased secretion of some anti-inflammatory cytokines, such as IL-1ra, and of cytokines with anti-tumour effect, such as IL-2 and IL-15." (PMID 20717114, 2010). "Importantly, the proliferation and anti-tumor activity of the transferred CD8+ T cells was entirely dependent on IL-2/IL-15 signaling, as demonstrated by genetic disruption of the IL-2 receptor alpha (CD25) or beta (CD122) subunits." (PMID 21203522, 2010). "In addition, some studies showed that tumor cells engineered to secrete IL15 can inhibit tumor growth on animal models." (PMID 19422685, 2009). "The robust GM-CSF and IFN-γ release induced by IL-15 and IL-21 in combination suggests that cytokine-differentiated NK cells may retain the ability to mount effective anti-viral and anti-tumour responses." (PMID 19712464, 2009). "The activating receptor NKG2D, whose ligands are frequently over-expressed in tumours from multiple origins, could be detected at very low levels in cultures performed with IL-15 alone." (PMID 19712464, 2009). "Mice that are deficient in IL-15 do not generate mature NK cells, and lack critical innate host defense and tumor defense functions." (PMID 16396683, 2006). "In vivo studies have recently demonstrated that interleukin 21 (IL-21) enhances the anti-tumor function of T-cells and NK cells in murine tumor models, and the combined use of IL-21 and IL-15 has resulted in prolonged tumor regression and survival in mice with previously established tumors." (PMID 16772043, 2006). "These cells express Cxcl9, Cxcl10 and Il15, but in contrast to type 1 conventional dendritic cells, which cross-present antigens, inflammatory monocytes obtain and present peptide–major histocompatibility complex class I complexes from tumour cells through ‘cross-dressing’." (PMID 39604727, 2025).